NFKBIA (NFKB inhibitor alpha)
Description:
Inhibits the activity of dimeric NF-kappa-B/REL complexes by trapping REL (RELA/p65 and NFKB1/p50) dimers in the cytoplasm by masking their nuclear localization signals. On cellular stimulation by immune and pro-inflammatory responses, becomes phosphorylated promoting ubiquitination and degradation, enabling the dimeric RELA to translocate to the nucleus and activate transcription.
Synonyms: IkappaBalpha; IKBA; NFKBI; MAD-3; EDAID2
Tractability: Small molecule: a high-quality ligand is known; it has a binding pocket of medium quality; it belongs to a druggable protein family. Antibody: its Gene Ontology location is reachable by antibodies, with high confidence. PROTAC: UniProt records ubiquitination sites on it; ubiquitination databases record sites on it; its protein half-life has been measured; a small molecule that binds it is known.
Target class: Other cytosolic protein
Safety:
Unwanted effects reported when the protein is acted on. In parentheses: how it was acted on, where the effect was seen, and who reports it.
diarrhea (source: ClinPGx)
hepatotoxicity (source: ClinPGx)
skin rash (source: ClinPGx)
Gene: Protein-coding gene on chromosome 14 (35,401,079 to 35,404,749, reverse strand). Ensembl gene ENSG00000100906.
Subcellular location: Cytoplasm; Nucleus
Subcellular location (Human Protein Atlas): Cytosol
Pathways (Reactome):
Immune System: Activation of NF-kappaB in B cells; CLEC7A (Dectin-1) signaling; Downstream TCR signaling; FCERI mediated NF-kB activation; Interleukin-1 signaling; RIP-mediated NFkB activation via ZBP1; TAK1-dependent IKK and NF-kappa-B activation; TRAF6 mediated NF-kB activation
Disease: Dengue virus modulates apoptosis; IkBA variant leads to EDA-ID; SARS-CoV-1 activates/modulates innate immune responses
Metabolism of proteins: SUMOylation of immune response proteins; Ub-specific processing proteases
Cellular responses to stimuli: Turbulent (oscillatory, disturbed) flow shear stress activates signaling by PIEZO1 and integrins in endothelial cells
Signal Transduction: NF-kB is activated and signals survival
Gene Ontology:
Molecular function: enzyme binding; identical protein binding; molecular sequestering activity; NF-kappaB binding; protein binding; protein sequestering activity; transcription regulator inhibitor activity; ubiquitin protein ligase binding
Biological process: canonical NF-kappaB signal transduction; interleukin-1-mediated signaling pathway; negative regulation of canonical NF-kappaB signal transduction; negative regulation of cholesterol transport; negative regulation of cytokine production involved in inflammatory response; negative regulation of lipid storage; negative regulation of macrophage derived foam cell differentiation; negative regulation of non-canonical NF-kappaB signal transduction; negative regulation of protein import into nucleus; negative regulation of transcription by RNA polymerase II; non-canonical NF-kappaB signal transduction; positive regulation of inflammatory response; positive regulation of transcription by RNA polymerase II; toll-like receptor 4 signaling pathway; tumor necrosis factor-mediated signaling pathway; cellular response to cold; B cell receptor signaling pathway; cellular response to cytokine stimulus; positive regulation of transcription initiation by RNA polymerase II
Cellular component: cytoplasm; cytosol; I-kappaB/NF-kappaB complex; nucleus; nucleoplasm
Genetic constraint (gnomAD): Loss-of-function variants: 10 observed, 33.94 expected, observed/expected ratio (o/e) 0.29, 90% interval 0.18 to 0.5. The synonymous counts are far from expectation, so gnomAD's model fits this gene poorly and the ratio says little. Missense variants: 355 observed, 390.99 expected, observed/expected ratio (o/e) 0.91, 90% interval 0.83 to 0.99. Synonymous variants: 205 observed, 162.31 expected, observed/expected ratio (o/e) 1.26, 90% interval 1.13 to 1.42.
Gene-disease validity (ClinGen):
ClinGen rates the evidence that NFKBIA causes each of these diseases.
ectodermal dysplasia and immunodeficiency 2 (autosomal dominant): Definitive.
Homologues: Orthologues: chimpanzee NFKBIA (99% identical), macaque NFKBIA (99% identical), pig NFKBIA (94% identical), dog NFKBIA (93% identical), guinea pig NFKBIA (93% identical), rabbit NFKBIA (92% identical), mouse Nfkbia (91% identical), Drosophila melanogaster cact (34% identical), Drosophila melanogaster mask (23% identical), Caenorhabditis elegans ipla-7 (18% identical), Caenorhabditis elegans mask-1 (16% identical), Drosophila melanogaster iPLA2-VIA (16% identical). Paralogues in human: NFKBIB (33% identical), TONSL (31% identical), PLA2G6 (21% identical), ANKRD22 (9% identical).
Diseases named in the same sentence as NFKBIA in open-access papers:
NFKBIA is named in the same sentence as 378 diseases in open-access papers, as found by Europe PMC text mining. Sharing a sentence is not in itself a finding about the gene and the disease. The quoted sentences say what the papers report.
breast cancer (109 papers, 2005 to 2026). A primary or metastatic malignant neoplasm involving the breast. "We examined the role of NFKBIA in the activity of NF-κB signaling and tumor associated inflammation in breast cancer." (PMID 35180863, 2022). "In a previous study, the NFKBIA gene (encoding the NF-κB inhibitor IκBα) was found to be deleted in 10.8% of breast cancer cases, and NFKBIA deletions were shown to be significantly associated with TNBC (present in 32.8% of cases)." (PMID 32328465, 2020). "Our report also presents the first evidence for the association of NFKBIA polymorphism with the risk of breast cancer in any Asian population." (PMID 25559835, 2014). "We searched the CTD database for associated genes and the potential targeted drugs and found that NFKBIA is most closely associated with breast cancer progression, with a gene inference score (with BC) of 220.02, followed by BCAP31 (inference score = 51.77), BMF (12.5), and GLUL (10.56)." (PMID 40281780, 2025). "For our purpose, MCF-7 breast cancer cells labeled with heavy amino acids were transfected with plasmid encoding IκBα protein (NFKBIA) resistant to degradation that inhibits transcriptional activity of NF-κB transcription factors and is also known as IκB-super-repressor." (PMID 38417630, 2024). "We found that rescuing the expression of NFKBIA in breast cancer cells with NFIL3 overexpression blocked the rapid translocation of NF-κB from the cytoplasm into the nucleus triggered by NFIL3 overexpression in Hs578T cells." (PMID 35180863, 2022). "Conversely, a significant relationship was observed between high expression of NFKBIA, which is otherwise underexpressed in radioresistant breast cancer cells, and favorable prognosis, indicated by an HR value <1." (PMID 33898418, 2021). "The well-known NFKB1 inhibitor alpha (NFKBIA) was shown to be a favorable predictor in breast cancer patients." (PMID 33898418, 2021). "One study investigated common variants within the gene coding region for NF-kappaB and IkappaB, NFKB1 and NFKBIA, for involvement in sporadic breast cancer." (PMID 31874600, 2019). "In the I-Kappa B kinase signaling pathway, our method found genes 4792 (NFKBIA), 23,476 (BRD4), and 79,155 (TNIP2) to be significantly associated with breast cancer survival." (PMID 31874600, 2019). "For pre-menopausal women, significant associations with breast cancer risk were observed for NFKB1 ins/del and del/del genotypes, NFKBIA CT genotype, IL-8 TT genotype, IL-10 TT genotype, and TNF c.-418 GA and AA genotypes." (PMID 25559835, 2014). "“All of the mouse and most human mammary tumors also displayed decreased expression of genes known to inhibit cell proliferation, including NFKBIA (IKBalpha), GADD45B, and CDKN1A (p21); transcription-related genes such as CEBP, JUN, JUNB, and ELF1;....”." (PMID 23216862, 2012). "Similarly, the phosphorylation of NFKBIA was correlated with the necroptosis in breast cancer cells." (PMID 38020922, 2023). "Furthermore, TCGA database analysis showed a significant correlation of NFKBIA and RORC expression in breast cancer, suggesting a regulatory role of RORs in IκBα transcription regulation." (PMID 35440077, 2022). "We analyzed not only the association of individual polymorphisms and breast cancer risk, but also the effects of combinations of functionally related polymorphisms (NFKB1 and NFKBIA; IL-8 and IL-10; and TNF c.-418 and c.-488), menopausal status, histopathological type, and cancer grading." (PMID 25559835, 2014). "NFKB1, NFKBIA, IL-8, IL-10, and TNF polymorphisms could serve as useful predictive biomarkers for breast cancer risk among women in East China." (PMID 25559835, 2014). "However, the results did not support an involvement of the NFKBIA polymorphisms in sporadic breast cancer in the Caucasian population." (PMID 31874600, 2019).
breast cancer (continued). "Although one of the real microgravity studies with human breast cancer cell lines indicated an upregulation of NFKB1, NFKB3, NFKBIA, and NFKBIB but a reduced protein content." (PMID 40577073, 2025). "For instance, NFKBIA mRNA levels positively correlated with the infiltration levels of M1 macrophages, CD4+ T cells, CD8+ T cells and naive B cells in breast cancer." (PMID 37775993, 2023). "Consistently, we analyzed the correlation between NFIL3 and NFKBIA in the TCGA dataset and found that NFIL3 mRNA was positively correlated with NFKBIA mRNA in both breast cancer and pancancer." (PMID 35180863, 2022). "In summary, NFIL3 protein is elevated in TNBCs compared with both normal breast tissues and other subtypes of breast cancer, and promotes the progression of TNBC cells by activating the NF-κB signaling pathway through suppressing the expression of NFKBIA." (PMID 35180863, 2022). "The cell experiment results suggested that NFKBIA played a protective role, while INHBA played the pro-cancer role in breast cancer." (PMID 35999846, 2022). "The correlation between NFKBIA protein levels and the amount of infiltrated M1, M2 and CD8+ T cells was also confirmed in breast cancer tissues using IHC assays." (PMID 35180863, 2022). "In fact, it has been observed that DNMT1 and E2F3 are candidate targets of miR-152 in HCC, endometrial and breast cancer; BTRC has been shown to ubiquitinate phosphorylated NFKBIA, targeting it for degradation and thus activating NF-κB." (PMID 25330074, 2014). "Moreover, we detected the protein levels of NFIL3 and NFKBIA in breast cancer tissues using IHC and revealed that the NFIL3 protein level was negatively correlated with the NFKBIA protein level in breast cancer tissues." (PMID 35180863, 2022). "In addition, we observed feedback loops concerning nuclear factor kappa B subunit 1 (NFKB1) activation (CHUK, NFKBIA; related to cell survival) in bladder cancer, anti-apoptotic BIRC2/3, and pro-apoptotic TRAF1 factors in breast cancer, respectively." (PMID 28775339, 2017). "In the BRCA samples of TCGA, we also noticed a significant relationship between AGR2 expression and FOXA1 gene copy number, as well as several cancer gene copy numbers localized at 14q such as NFKBIA, SAV1, CHD8 or AJUBA, which are not known as driver oncogenes or TSG in breast cancer." (PMID 35857928, 2022).
glioblastoma (53 papers, 2012 to 2025). The most malignant astrocytic tumor (WHO grade IV). "Somatic mutations in TNIP1 (encoding ABIN-1) have also been found in various human lymphomas, while somatic mutations in NFKBIA (encoding IκBα) have been observed in Hodgkin's disease and in glioblastomas." (PMID 34269817, 2021). "A different mutation in NFKBIA has also been associated with decreased IκB-α protein levels and the presence of at least two smaller molecular weight IκB-α bands in gels in patients with glioblastoma multiforme." (PMID 32781504, 2020). "In the present study, using gene sequencing, we identified rs1957106 as a novel single nucleotide polymorphism (SNP) in NFKBIA in glioblastoma and found that it was more frequently present in glioblastoma patients." (PMID 25215581, 2014). "Meanwhile, NF-κB inhibitor-α (NFKBIA), which represses NF-κB, is associated with distal metastasis of oral squamous cell cancer and glioblastoma." (PMID 24504166, 2014). "The SNP rs1957106 CT and TT genotypes were found to be associated with lower NFKBIA protein levels and a poor prognosis of pateints with glioblastoma." (PMID 25215581, 2014). "Other studies have associated the deletion of NFKBIA with glioblastoma multiforme and Hodgkin’s lymphoma specimens." (PMID 24391818, 2013). "Loss of NFKBIA function results in NFκB activation, which contributes to glioblastoma progression." (PMID 38264122, 2023). "Likewise, Bredel and coworkers demonstrated that deletion of NFKBIA is associated with short survival of patients suffering from glioblastoma." (PMID 34440811, 2021). "Deletion of the NFKBIA gene or low expression of IκBα protein serves as a major mechanism of permanent NF‐κB activation in a non‐classical form of glioblastoma, where it is associated with poor prognosis in patients and resistance to proteasome and IKK inhibitors in clinical trials." (PMID 33459422, 2021). "In addition to allelic loses, a single-nucleotide polymorphism in exon 1 of NFKBIA, which leads to reduced expression of IκBα, is more frequently present in glioblastoma patients than in the healthy population and is associated to poor prognosis." (PMID 34572464, 2021). "Given that NFKBIA modulates NF-κB activity in physiological and pathophysiological processes and that there are polymorphisms of NFKBIA in several types of cancer, the present study aimed to investigate the genotype of NFKBIA in glioblastomas and whether this is associated with its expression." (PMID 25215581, 2014). "Accordingly, glioblastoma patients with NFKBIA deletion show reduced survival rates, as shown by Bredel and colleagues." (PMID 35203471, 2022). "In particular, the 790 human glioblastomas analyzed by Bredel and coworkers revealed either an EGFR amplification or an NFKBIA deletion, with heterozygous deletions of NFKBIA being present in 28% of glioblastomas and in 22% of cancer stem-like cells." (PMID 35203471, 2022). "In vitro experiments using glioblastoma cell lines demonstrated that the reintroduction of NFKBIA gene or IκBα protein by nanoparticles induced apoptosis and increased the sensitivity of tumor cells to chemotherapy." (PMID 34572464, 2021). "By comparing 790 human glioblastomas, the authors reported NFKBIA deletion in glioblastoma to result in clinical outcomes comparable to EGFR amplification." (PMID 34440811, 2021). "They report heterozygous deletion of NFKBIA in up to 28% of glioblastomas in their study and in 22% of cancer stem-like cells." (PMID 34440811, 2021). "The enforced expression of NFKBIA in both glioblastomas showing low NFKBIA expression or in those overexpressing EGFR, but with normal NFKBIA, resulted in inhibition of tumor growth." (PMID 30279357, 2018). "The NFKBIA protein levels detected by western blot analysis (using 100 ng of sample) were significantly lower in the glioblastomas harboring the SNP rs1957106 CT and TT genotypes than in the samples harboring the SNP rs1957106 CC genotype." (PMID 25215581, 2014).
glioblastoma (continued). "We observed that the relative copy number of NFKBIA was significantly lower in 7 of the 10 glioblastomas, all of which had the SNP rs1957106 CT and TT genotypes and low NFKBIA protein levels." (PMID 25215581, 2014). "In conclusion, and to the best of our knowledge, the findings of the present study provide the first evidence that the rs1957106 SNP in NFKBIA is frequently present in glioblastoma patients." (PMID 25215581, 2014). "The aberrant constitutive activation of nuclear factor-κB (NF-κB) has been observed in glioblastomas, while NF-κB inhibitor alpha (NFKBIA) inhibits the NF-κB signaling pathway under several physiological processes." (PMID 25215581, 2014). "Recent data described heterozygous deletions of the NF-kB Inhibitor alpha gene (NFKBIA) in about 20% of glioblastomas (GBM): deletions were mutually exclusive with epidermal growth factor receptor (EGFR) amplification, a frequent event in GBM." (PMID 24330732, 2013). "NFKBIA is an inhibitor of NFκB and suppresses glioblastoma tumors." (PMID 38264122, 2023). "Reduced IκBα levels in glioblastoma was not linked to mutations in the coding or promoter regions of the NFKBIA gene, but to gene copy number alterations." (PMID 34572464, 2021). "Interestingly, forced expression of NFKBIA by retroviral transduction of established glioblastoma cell lines inhibited signs of malignant transformation such as growth, migration, and colony formation." (PMID 34440811, 2021). "Interestingly, a recent genetic analysis showed deletion of the IκBα (NFKBIA) gene in up to 24% of glioblastoma patients." (PMID 31083587, 2019). "Importantly, the presence of NFKBIA deletions at the level of cancer stem cells suggests that these deletions can emerge early in the pathogenesis of glioblastoma." (PMID 30279357, 2018). "Genetic changes in NFKBIA are involved in colorectal and glioblastoma tumorigenesis." (PMID 25475428, 2014). "Therefore, considering that NFKBIA plays pivotal roles in the regulation of the NF-κB signaling pathway, in the present study, we focused on the role of NFKBIA in glioblastomas." (PMID 25215581, 2014). "Hence, by identifying rs1957106 as a novel SNP in NFKBIA in glioblastoma patients, we provide a new platform for further investigating the function of NFKBIA in the pathobiology of glioblastoma." (PMID 25215581, 2014). "To determine whether deregulation of negative regulators of NF-κB has a role in constitutive NF-κB activation in glioblastoma, we analyzed expressions of the NF-κB regulators NFKBIA, TNFAIP3, TNIP1 and TNIP2 in glioblastoma patients from The Cancer Genome Atlas (TCGA)." (PMID 28166199, 2017). "However, to the best of our knowledge, there is still no relative study available to date on the association between the genotype and expression of NFKBIA, while the genotype of NFKBIA in glioblastomas remains unclear." (PMID 25215581, 2014). "Thus, our data support a role for NFKBIA in the suppression of glioblastoma tumors." (PMID 25215581, 2014). "In addition, current data provide evidence for a tumor suppressor role of NFKBIA in glioblastomas." (PMID 25215581, 2014). "Furthermore, the NFKBIA mRNA levels were significantly lower in the glioblastomas harboring the SNP rs1957106 CT and TT genotypes than in the samples harboring the SNP rs1957106 CC genotype (CT/TT 0.31±0.11 vs. CC 0.54±0.18 vs. non-cancerous 0.78±0.12, P<0.001)." (PMID 25215581, 2014). "However, the contribution of NFKBIA to glioblastomas is poorly understood." (PMID 25215581, 2014). "In both glioblastoma cell lines, depletion of FOS, NFKB inhibitor alpha (NFKBIA) and EGFR resulted in similar basal clonogenic and clonogenic radiation survival compared to Lpd depletion." (PMID 34771501, 2021). "Thus, NFKBIA mRNA is probably a target of miR‐196a in EAC, as it is in pancreatic cancer and glioblastoma." (PMID 40955778, 2025).